B2M (beta-2-microglobulin)
Description:
Component of the class I major histocompatibility complex (MHC). Involved in the presentation of peptide antigens to the immune system. Exogenously applied M.tuberculosis EsxA or EsxA-EsxB (or EsxA expressed in host) binds B2M and decreases its export to the cell surface (total protein levels do not change), probably leading to defects in class I antigen presentation.
Synonyms: AMYLD6; IMD43; MHC1D4
Tractability: Small molecule: a structure with a bound ligand is known; it has a high-quality binding pocket. Antibody: UniProt places it where antibodies can reach, with high confidence; its Gene Ontology location is reachable by antibodies, with high confidence; UniProt predicts a signal peptide or a membrane-spanning region; the Human Protein Atlas places it where antibodies can reach. PROTAC: ubiquitination databases record sites on it; its protein half-life has been measured.
Gene: Protein-coding gene on chromosome 15 (44,711,253 to 44,718,851, forward strand). Ensembl gene ENSG00000166710.
Subcellular location: Secreted; Cell surface
Subcellular location (Human Protein Atlas): Golgi apparatus; Plasma membrane; Cytosol; Predicted to be secreted
Pathways (Reactome):
Immune System: Antigen Presentation: Folding, assembly and peptide loading of class I MHC; DAP12 interactions; DAP12 signaling; ER-Phagosome pathway; Endosomal/Vacuolar pathway; Immunoregulatory interactions between a Lymphoid and a non-Lymphoid cell; Interferon gamma signaling; Neutrophil degranulation
Disease: Modulation by Mtb of host immune system; Nef mediated downregulation of MHC class I complex cell surface expression; SARS-CoV-2 activates/modulates innate and adaptive immune responses
Metabolism of proteins: Amyloid fiber formation
Gene Ontology:
Molecular function: identical protein binding; protein binding; protein homodimerization activity; structural molecule activity; MHC class II protein complex binding; peptide antigen binding
Biological process: amyloid fibril formation; antigen processing and presentation of endogenous peptide antigen via MHC class I; antigen processing and presentation of exogenous peptide antigen via MHC class Ib; cellular response to iron ion; cellular response to nicotine; intracellular iron ion homeostasis; learning or memory; negative regulation of epithelial cell proliferation; negative regulation of forebrain neuron differentiation; negative regulation of iron ion transport; negative regulation of neurogenesis; negative regulation of receptor-mediated endocytosis; peptide antigen assembly with MHC class I protein complex; positive regulation of cellular senescence; positive regulation of receptor-mediated endocytosis; positive regulation of T cell cytokine production; protein homotetramerization; regulation of iron ion transport; transferrin transport; antigen processing and presentation of exogenous peptide antigen via MHC class II; peptide antigen assembly with MHC class II protein complex; positive regulation of immune response; positive regulation of T cell activation; regulation of natural killer cell mediated immunity; immune response; and 2 more
Cellular component: cell surface; extracellular exosome; extracellular region; focal adhesion; Golgi apparatus; HFE-transferrin receptor complex; membrane; MHC class I peptide loading complex; MHC class Ib protein complex; plasma membrane; early endosome lumen; early endosome membrane; endoplasmic reticulum; endoplasmic reticulum lumen; ER to Golgi transport vesicle membrane; Golgi membrane; late endosome membrane; lysosomal membrane; MHC class I protein complex; MHC class II protein complex; phagocytic vesicle membrane; recycling endosome membrane; specific granule lumen; tertiary granule lumen; external side of plasma membrane
Genetic constraint (gnomAD): Loss-of-function variants: 3 observed, 15.47 expected, observed/expected ratio (o/e) 0.19, 90% interval 0.087 to 0.5. The upper end of that interval is the gene's LOEUF score, 0.5, which puts it in group 2 of 6, group 1 being the genes least tolerant of losing a copy. Missense variants: 107 observed, 149.15 expected, observed/expected ratio (o/e) 0.72, 90% interval 0.61 to 0.84. Synonymous variants: 45 observed, 56.46 expected, observed/expected ratio (o/e) 0.8, 90% interval 0.63 to 1.02.
Gene-disease validity (ClinGen):
ClinGen rates the evidence that B2M causes each of these diseases.
hypoproteinemia, hypercatabolic (autosomal recessive): Limited.
Cancer hallmarks: escaping immune response to cancer (suppresses)
Homologues: Orthologues: macaque B2M (92% identical), chimpanzee B2M (81% identical), pig B2M (71% identical), rabbit B2M (70% identical), mouse B2m (68% identical), dog B2M (67% identical), guinea pig B2M (67% identical), rat B2m (62% identical), zebrafish zmp:0000001138 (37% identical). Paralogues in human: HLA-DPA1 (34% identical), HLA-DQA1 (30% identical), HLA-DQA2 (30% identical), HLA-DRB1 (30% identical), HLA-DRB5 (29% identical), HLA-DOA (28% identical), HLA-DQB1 (28% identical), HLA-DQB2 (28% identical), HLA-DMB (27% identical), HLA-DOB (27% identical), HLA-DPB1 (27% identical), HLA-DRA (27% identical), and 1 more.
Diseases named in the same sentence as B2M in open-access papers:
B2M is named in the same sentence as 351 diseases in open-access papers, as found by Europe PMC text mining. Sharing a sentence is not in itself a finding about the gene and the disease. The quoted sentences say what the papers report.
melanoma (118 papers, 2013 to 2026). A malignant, usually aggressive tumor composed of atypical, neoplastic melanocytes. "Benitez’s study discovered that two melanoma patients who were refractory to MAGE-peptide tumor vaccine treatment with loss of B2M expression." (PMID 40191187, 2025). "A melanoma patient with B2M defeat developed resistance subsequent to receiving PD-1 inhibitor, whereas a high level of B2M mRNA was linked to enhanced response to PD-1-based immunotherapy." (PMID 40191187, 2025). "It is widely recognized that the altered presentation of antigens induced by the alteration or loss of B2M expression is associated with an increased risk of metastasis in various cancers, including melanoma and sarcoma." (PMID 40725113, 2025). "In advanced melanoma, it was determined that 29.4% of patients exhibited B2M gene mutation, deletion, or LOH; similarly, HLA LOH was detected in 40% of non-small cell lung cancer (NSCLC) patients." (PMID 40191187, 2025). "Only melanoma samples displayed a relatively modest decrease in B2M loss, with 21% loss in primary to 14% loss in metastatic disease." (PMID 38455061, 2024). "In baseline and progressive melanoma tumour sampling, acquired resistance was associated with loss-of-function mutations in beta-2 microglobulin (b2M), a stabilising component of HLA class I complexes." (PMID 39534871, 2024). "This phase III trial included all patients with melanoma and was not limited to tumors with B2M loss or other biomarkers of MHC1 function." (PMID 39271499, 2024). "Pigs set in place an immune response during progression with dense infiltration by myeloid cells while melanoma cells are deficient in B2M expression." (PMID 38649394, 2024). "Beta-2-microglobulin (B2M) is another protein involved in antigen presentation that was implicated in the onset of resistance to immunotherapy in melanoma patients." (PMID 38672652, 2024). "In dMMR/MSI colorectal cancer and melanoma, genomic alterations in antigen-presenting machinery, including loss of beta-2-microglobulin and human leukocyte antigen (HLA) genes, are associated with resistance to checkpoint blockade." (PMID 38653864, 2024). "B2M inactivation by mutation is considered a key point in the resistance to checkpoint inhibitors in melanoma." (PMID 37686682, 2023). "Acquired B2M mutations and loss of B2M expression have been implicated as causes of acquired resistance to immunotherapy in melanoma." (PMID 37686520, 2023). "B2M mutations resulting in decreased MHC I expression are a well-described acquired resistance mechanism to PD-1/PD-L1 ICB in melanoma." (PMID 37371815, 2023). "Co-expression and correlation profile of B2M with CD1D, CD1B, and FCGRT dissociates in melanoma patients following B2M expression loss." (PMID 37077920, 2023). "One patient exhibited B2M loss of heterozygosity (LOH) and two frameshift mutations, and another melanoma patient had two frameshifts B2M changes at the time of disease progression." (PMID 37038154, 2023). "In five cell lines derived from metastatic melanomas with functional loss of beta-2-microglobulin expression, replacement of beta-2-microglobulin was shown to restore antigen processing capabilities of the cells and recognition of tumor by T cells." (PMID 37627127, 2023). "Here we summarize resistance to different immunotherapeutic approaches caused by B2M disruption in melanoma and promising treatment strategies to overcome it." (PMID 36046045, 2022). "Many molecular mechanisms can lead to complete loss of MHC class I antigen expression, while alterations in the B2M gene have been demonstrated to be the major cause in melanoma." (PMID 36046045, 2022). "Loss of MHC class I expression in the majority (>50% of cells) of melanoma cells was observed in 78 of these patients and associated with transcriptional downregulation of HLA and B2M genes." (PMID 36046045, 2022).
melanoma (continued). "Meanwhile, additional studies about new therapeutic strategies for B2M-deficient melanoma are still needed to pave the way for advanced melanoma control and eradication." (PMID 36046045, 2022). "In a small proportion of melanomas, loss of HLA class I expression is caused by mutation of the B2M gene; however, epigenetic mechanisms or translational dysregulation are much more frequent mechanisms of HLA class I loss in cancers." (PMID 35628196, 2022). "Namely, JAK1/2 mutations were associated with decreased Interferon-γ (IFN-γ) sensitivity of melanoma cells, and mutations in the gene encoding beta-2-microglobulin (B2M) to loss of surface expression of MHC-I and decreased antigen presentation." (PMID 35432344, 2022). "Here we describe how β2M is involved in MHC class I-restricted tumor antigen presentation, different genetic mechanisms of B2M alterations in melanoma tissues and cell lines, and the impact of β2M deficiency on anti-melanoid immune responses and immunotherapy." (PMID 36046045, 2022). "A subsequent study confirmed that B2M mutations can result in immune selection and expansion of highly aggressive melanoma clones." (PMID 33960680, 2021). "For instance, mutations in the B2M gene are typical for melanoma and MSI-H colorectal carcinoma, while a transcriptional downregulation of HLA-I can be frequently detected in bladder cancer." (PMID 34680201, 2021). "In melanoma, it has been reported that B2M mutations lead to HLA‐class‐I antigen loss, which in turn promotes tumor cells to progress into the malignant phenotype." (PMID 33960680, 2021). "Loss of MHC class I expression is another established mechanism of immune escape, often involving genetic alterations in the B2M gene and we noted that the SMU15-0217 melanoma cell line showed loss of B2M expression, concurrent with loss of HLA-ABC expression." (PMID 29977240, 2018). "Studies have reported that one of the major causes of melanoma includes the loss-of-function mutations of B2M." (PMID 28813459, 2017). "B2M mutations were associated with higher estimates of NK cells in melanoma (effect size 1.3, -logP = 1.8) and lung adenocarcinoma (effect size 1.3, -logP 2 = 2)." (PMID 28749946, 2017). "Loss of B2M was also observed previously in melanoma patients treated with ex vivo expanded CD8+ T cells and IL-2." (PMID 29121062, 2017). "One explanation for our diverging results may be due to our studies being conducted on a diverse range of tumors while these reports linking B2M loss to immunotherapy resistance was done in melanoma and lung adenocarcinoma." (PMID 38455061, 2024). "Whole-exosome sequencing assessment of baseline and relapsed tumors from four patients with melanoma who developed resistance to anti-PD-1 therapy after the initial response identified an acquired homozygous truncating mutation in the gene encoding B2M at relapse in one patient." (PMID 37614504, 2023). "B2M mutations are closely associated with patient progression on immunotherapy in melanoma." (PMID 36046045, 2022). "Melanoma cell lines with B2M mutation may lose IFN-γ-mediated MHC class I inducibility, thereby supporting tumor evasion of immune surveillance." (PMID 36046045, 2022). "In melanoma cell lines, it has been reported that B2M mutations lead to HLA‐class‐I antigen loss, which might be an early event for tumor cells progressing into the malignant phenotype." (PMID 33960680, 2021). "Beta-2 microglobulin (B2M) mutations can also have an impact on the response to ICB in melanoma." (PMID 33777757, 2021). "Melanoma cells with JAK1/2 deletion are resistant to IFN-induced anticancer activity, whereas melanoma cells with B2M loss block melanoma cells from being recognized by antigen-specific T cells and maybe therefore resistant to cytotoxicity." (PMID 34804979, 2021). "In melanoma, B2M loss has been associated with resistance to immune checkpoint inhibitors." (PMID 34197832, 2021).
melanoma (continued). "In melanoma, B2M mutation was also associated with resistance of T cell and PD-1 blockage." (PMID 33658560, 2021). "However, at the same time, the peculiarity of MMRd tumors is largely confirmed, since a mechanism of secondary resistance to CPIs (B2M loss) in melanoma and lung cancer is confuted in MMRd tumors." (PMID 34072037, 2021). "Mutations in cancers other than HCC associated with a negative outcome for ICI treatment include inactivating mutations in JAK1/2 or beta-2-microglobulin in melanoma, MDM4 amplifications, or EGFR alterations in different stage IV tumors or STK11/LKB1 alterations in KRAS-mutant lung adenocarcinoma." (PMID 33353145, 2020). "Early studies found evidence that melanoma patients who initially responded to cytokines and adoptive T cell-based therapies developed secondary resistance through cancer cell loss of beta-2 microglobulin (B2M), the subunit necessary for antigen presentation by MHC class I molecules." (PMID 31703593, 2019). "Previous studies have shown that the vast majority of B2M gene mutations detected in human malignant tumors are point mutations and microdeletions (a few bases), except for a large (~6 kb) deletion identified in the melanoma cell line FO-1." (PMID 30648121, 2018). "Moreover, in post-treatment samples, mutations in JAK1, JAK2, and B2M were recently proposed as mechanisms of acquired resistance in three melanoma patients treated with anti-PD-112." (PMID 29070816, 2017). "We thus developed a mouse model to test whether natural killer cells would selectively kill B2M-deficient melanoma cells." (PMID 29070816, 2017). "Finally, we observe mutations in beta-2 microglobulin (B2M), a necessary component of antigen presentation, associated with high estimates of NK cells in melanoma, and JAK2 mutations with higher NK levels in colon cancer." (PMID 28749946, 2017). "It is known that mutations in B2M would impact tumor neoantigen presentation and immune activation B2M-mutated CRCs have been shown to be associated with higher levels of PD-1 positive T cells, pointing toward potential PD-1 inhibitor resistance (as has already been observed in melanoma)." (PMID 36531239, 2022). "Moreover, the imbalance between activating and inhibitory signals decreases NK cell cytotoxicity against malignant cells, supported by a less robust activity of tissue-infiltrating NK cells in solid tumors and low levels of MICA and ULBP expression in some B2M-deficient melanoma cell lines." (PMID 36046045, 2022). "Mutations in the B2M gene may appear at the early stage of melanoma development." (PMID 32517213, 2020). "B2M loss has been frequently observed in patients who show initial sensitivity to ICB but subsequently relapse, particularly in melanoma, lung cancer, and colorectal cancer." (PMID 40673641, 2025). "Analysis of DC2s and DC3s from melanoma patients for surface expression of B2M showed a strong increase in B2M expression on DC3s, thereby supporting our in vitro findings using in vivo developed ti-DC3s." (PMID 40789452, 2025). "These two melanoma cases exhibited homozygous deletions in B2M, a strong predictor of ICI-resistance, and both were indeed non-responders with progressive disease." (PMID 41463470, 2025). "Previous studies have demonstrated that histone deacetylase inhibitor (HDACi) can reverse immune resistance by upregulating the expression of genes pertinent to antigen processing and presentation pathways (including B2M) in melanoma cell lines." (PMID 40191187, 2025). "Exemplary knockdown of NLRC5 and B2M by siRNA in three different melanoma cell lines confirmed that downregulation of the IFN-γ-induced STAT1 pathway indeed significantly impairs HLA-C expression and Vα3S1/Vβ13S1 TCR stimulation." (PMID 40243413, 2025). "Our findings indicate a positive correlation between tumor‐intrinsic IL4I1 expression and the expression of HLA‐A/‐B/‐C, B2M, and genes associated with CTL activation (GZMB, GZMA, CD8A, IFNG) in melanoma patients." (PMID 40583248, 2025).